CXCL1 (C-X-C motif chemokine ligand 1)
Diseases named in the same sentence as CXCL1 in open-access papers (continued):
Sharing a sentence is not in itself a finding about the gene and the disease.
bacterial infection (continued). "Particularly, despite failure to control bacterial infection, the P-DIE mice were shown to produce high levels of CXCL1 and CXCL2 in the peritoneum and blood that promoted neutrophil infiltration." (PMID 34367170, 2021). "As expected, bacterial infection induced a systemic inflammatory response characterized by increased plasmatic levels of TNFα, IL-6, IL-12, IFNγ and KC/GRO (CXCL-1) compared to PBS-treated mice." (PMID 34437647, 2021). "The data presented here indicate that L-1R signaling is essential for CXCL1 and CXCL2 production upon exposure to GAS and S. aures and for neutrophil recruitment in a major target organ during bacterial infection." (PMID 33525468, 2021). "The predominant cell types in the lung expressing the two CXCL-8 homologs CXCL-1 and CXCL-2 during bacterial infections are alveolar macrophages and pulmonary epithelial cells." (PMID 25033194, 2014). "Moreover, the experimental results indicate that IL-1 signaling promotes the production of leukocyte attractant chemokines CXCL-1 and CXCL-2 and recruitment of neutrophils to bacterial infection sites." (PMID 33525468, 2021). "For example, LTβR−/− mice are sensitive to bacterial infection due to the absence of lymphoid organs in these mice, and LTβR signaling in intestinal epithelial cells is required for the recruitment of neutrophils to the site of infection during early infection via the production of CXCL1 and CXCL2." (PMID 30469426, 2018). "Recently, it has been shown that DAMPs could induce inflammatory responses through the production of IL-6 and chemokine (C-X-C motif) ligand 1 (CXCL1) and the release of cathepsin B, in the absence of any bacterial infection or products in cultured mouse mixed glia." (PMID 27127546, 2016).
inflammation (34 papers, 2013 to 2025). Aberrant reaction of the microcirculation characterized by movement of fluid and leukocytes from the blood into extravascular tissues. "At day 3 post-exposure, 50 μg per mouse of Nano-Ni caused acute lung inflammation and injury that were reflected by increased neutrophil count, CXCL1/KC level, LDH activity, concentration of total protein, and MMP-2/9 protein levels and activities in the BALF." (PMID 30616599, 2019). "It is well-known that chemokine production is a critical step associated with leukocyte accumulation in the lungs, and CXCL1/KC is considered important neutrophil chemo-attractants released in the lungs in many animal models of airway inflammation, induced by exposure to various particles." (PMID 30616599, 2019). "In line with our findings, it has previously been shown that blockade of CXCR2, the principal neutrophil cognate receptor for CXCL1, suppresses neutrophil infiltration and exerts protection against lung inflammation in aged mice." (PMID 38918502, 2024). "In line with results from the RV‐induced airway inflammation model, increased mRNA expression of Cxcl1, Cxcl2, and Ifitm1 in HDM‐stimulated Mir146a/b−/− splenocytes was detected." (PMID 34185416, 2021). "Our results showed that exposure to Nano-Ni leads to severe acute lung injury and lung inflammation reflected by increased number of neutrophils, CXCL1/KC, LDH activity, and total proteins in BALF, which was confirmed by histopathological examination." (PMID 30616599, 2019). "In the murine subcutaneous air pouch model of acute gouty inflammation, arhalofenate significantly inhibited leukocyte or neutrophil infiltration and production of IL-1β, IL-6, and CXCL1 induced by MSU crystals." (PMID 30189890, 2018). "In agreement with our previous studies, the combined fracture and thoracic trauma resulted in a pulmonary inflammation in WT mice, as confirmed by increased C3a, IL-6 and chemokine (C-X-C motif) ligand 1 (CXCL1) concentrations 21,24." (PMID 29070810, 2017). "In intestinal inflammation, high level of CXCL-1 recruits neutrophil and aggravates intestinal injury." (PMID 27579035, 2016). "In an ozone-induced model of airway inflammation the CXCR2 antagonist SB-656933 inhibited CXCL1-induced CD11b expression on peripheral blood neutrophils and reduced neutrophilic inflammation in sputum." (PMID 23834268, 2013). "In contrast, high dose IT IL-6 resulted in marked anti-inflammatory effects as judged by reduced BAL fluid cytokines (IL-6, CXCL1, TNF-α), lung inflammation (IL-6, CXCL1, IL-1β), and serum CXCL1." (PMID 23667439, 2013). "It is also expected that curtailing the establishment of pancreatic inflammation by reducing the intra-pancreatic production of IL-6, CXCL1, and MCP-1, would lead to significantly reduced T-cell proliferation and chemotaxis, recruitment of neutrophils, and macrophages, respectively." (PMID 37180135, 2023). "In conclusion, DEP may contribute to neutrophilic lung inflammation pathogenesis by modulating ER stress-mediated CXCL1/KC expression in AM." (PMID 33371364, 2020). "The inhibition of both IL-6 and KC/CXCL1 may be important in decreasing neutrophilic airway inflammation augmented by ambient PM." (PMID 29882826, 2018). "In conclusion, this study shows that NLRP3 activation in neutrophils induces brain inflammation through neutrophil infiltration and BBB disruption via CXCL1/2 secretion and subsequent activation of the CXCL1/2-CXCR2 signaling axis." (PMID 40413505, 2025). "IRAK1 plays a major function in mediating the release of TNF-α, MIP-2, CXCL1, and IL-17 cytokines along with the MAPK pathway in airway inflammation, which leads to alveolar wall thickening and accumulation of collagen fibers." (PMID 36678340, 2023).
inflammation (continued). "In a model of organic dust-induced airway inflammation, TLR2 knockout mice had significantly lower airway neutrophils, IL-6, TNF-α, and CXCL-1 (mouse homolog of CXCL8) compared with wild-type controls suggesting that airway inflammation is dependent on TLR2." (PMID 23606791, 2013). "Additionally, the concentrations of CXCL-1, a neutrophil chemoattractant, the frequency of CD4+IL-17+ cells and the pulmonary inflammation were increased in the lungs during the comorbidity compared to the WT OVA group." (PMID 37445595, 2023). "Lung inflammation was more severe with the whole-body CS exposure system as shown by an enhanced lymphoid presence in BAL, lymph nodes and the upregulation of cytokine (IL-6) and chemokine (CXCL1) mRNA expression in the lung." (PMID 33731130, 2021). "SIRS was assessed by serum proinflammatory cytokines (TNF-α, IL-1β, CXCL1, IL-6), ALI was assessed by lung inflammation (lung myeloperoxidase [MPO] activity), and AKI was assessed by serum creatinine, BUN, and glomerular filtration rate (GFR) (by FITC-labeled inulin clearance) at 4 hours." (PMID 24265742, 2013). "Chemokines, such as CXCL-1 and MIP2 (CXCL-2), are major neutrophil chemoattractants that are produced in the lung in an airway inflammation model induced by DEP exposure; an increase in the pulmonary expression of these C-X-C chemokines exacerbated airway inflammation." (PMID 37836429, 2023). "Thus, our results suggest that chemokine CXCL1/KC released in DEP-stimulated AM might, at least in part, influence neutrophilic lung inflammation." (PMID 33371364, 2020). "The reduced bacterial burden observed in mice treated with LPS was associated to a reduced pulmonary inflammation as shown by a lower neutrophil number in BALF and lungs and a decreased mRNA expression of the pro-inflammatory genes Tnfα and Il-6, but not Il-1β and Cxcl1, in lungs." (PMID 35493510, 2022).
kidney (13 papers, 2012 to 2025). "Our scRNA‐seq data, along with recent studies in acute kidney injury, supported the notion that CXCL1 is highly expressed by profibrotic and inflammatory TECs, thereby contributing to inflammation in kidney disease and promoting fibrosis." (PMID 39492831, 2024). "The LMP7-dependent up-regulation of CXCL1, CXCL2, CXCL3 and VCAM-1 expression leads to alternations in the microenvironment of tumors and progression of colorectal carcinogenesis." (PMID 28881574, 2017). "This correction of critical metabolic pathways on gene expression level was accompanied by a significant decrease in histological liver inflammation, and suppression of FFD‐stimulated cytokine and chemokine proteins KC/CXCL1, MCP‐1/CCL2, and MIP‐2/CXCL2 and their pathways." (PMID 35830259, 2022). "CXCL1 levels in the plasma, however, remained unchanged upon inhibition of PARP-1 after liver IR." (PMID 29179487, 2017).
adenocarcinoma (11 papers, 2011 to 2023). A common cancer characterized by the presence of malignant glandular cells. "The results confirmed that CXCL1 expression in serum was considerably elevated in adenocarcinoma compared with normal samples (P = 0.0001)." (PMID 31998654, 2019). "The level of CXCL1 in the peripheral blood of adenocarcinoma patients also significantly elevated and positively related with clinical stage." (PMID 31998654, 2019). "The CXCL1 concentration in the serum of adenocarcinoma patients was measured by ELISA." (PMID 31998654, 2019). "To compare human ASC response with CXCL1 and CXCL8, we used conditioned medium from human DU145 adenocarcinoma cells that secrete both chemokines." (PMID 27241286, 2016).
kidney disease (11 papers, 2012 to 2024). "Consistent with previous findings, we have confirmed upregulation of several inflammatory mediators, including those modulated by NLRP2, namely Il6, Cxcl1 and Cxcl5 at early and late stages of the kidney disease." (PMID 38633264, 2024). "CXCL1, a chemokine belonging to the class of CXC chemokines, causes damage to other cells in kidney diseases, in addition to its function as a neutrophil chemoattractant." (PMID 35935760, 2022). "We found here that the activation of IL-1R1 in human mesangail cells induced a transient but robust up-regulation of CXCL1, 2, and 8, suggesting that IL-1 gene cluster may involve in the pathogenesis of renal diseases by induction of CXC chemokines." (PMID 26648169, 2015). "In addition, our experiments show that CaD prevents the increase and upregulation/activation of several pro-inflammatory cytokines (IL-6, CXCL1, IL-1ß, TNF-α, and MCP-1) that play a significant role in renal-disease progression." (PMID 31935212, 2020).
cardiovascular disease (9 papers, 2015 to 2025). "CXCL1 may promote cardiac remodeling and fibrosis, as well as be a therapeutic target for the treatment of cardiac fibrosis in cardiovascular disease." (PMID 36035865, 2022). "Besides, we probe the possibility that CXCL1 can be a therapeutic target for the treatment of cardiac fibrosis in cardiovascular diseases." (PMID 33996954, 2021).
neurological disorders (6 papers, 2011 to 2024). "For that reason, it is not surprising that chemokines such as CXCL1 and CCL2, among others, have been implicated in a number of neurological diseases." (PMID 37371384, 2023). "Furthermore, all the cytokines/chemokines, with the exceptions of CXCL1, CXCL6, and IL-17A, were detected at higher levels in the patients with LNB, as compared to the patients with “other neurological and non-neurological disorders”." (PMID 31877982, 2019).
immune disorders (5 papers, 2021 to 2026). "CXCL1 has been extensively implicated in the molecular pathophysiology of diverse disease states, particularly through its critical involvement in inflammatory cascades, immune diseases and tumors." (PMID 40176796, 2025).
liver (5 papers, 2017 to 2023). "To address this gap, we have reviewed the significance of CXCL1 in tumors, with a focus on gastrointestinal tumors due to the sheer volume of available information." (PMID 37408240, 2023). "CXCL1 plays a significant role in the molecular processes of gastrointestinal tumors." (PMID 37408240, 2023).
infectious disease (4 papers, 2016 to 2025). A disorder directly resulting from the presence and activity of a microbial, viral, or parasitic agent in humans. "We checked the expression of CXCR2, which is the main chemokine receptor on neutrophils for CXCL1 and CXCL2, because expression of CXCR2 is critically important for neutrophil associated protection against various infectious diseases." (PMID 28817707, 2017).
retinopathy (4 papers, 2012 to 2023). "Since oxidative stress is a hallmark of retinopathy, we next examined the effect of anti-CXCL1 treatment on ROS production with DHE (dihydroethidium) staining." (PMID 35981418, 2022). "The IL-33-NF-κB-VCAM-1-JunB-IL-8/CXCL1 signaling unravels the advanced strategies in the amelioration of proliferative retinopathies." (PMID 37179352, 2023). "Interestingly, a recent study reported that CXCL1 is crucial for retinal leukocyte recruitment and ischaemia/reperfusion (I/R)-induced retinopathy." (PMID 35981418, 2022).
colonic polyps (2 papers, 2024). "Validation by qRT-PCR confirmed increased expression of the LCN2, IL1B, CXCL1, and CXCL3 genes in CCS colonic polyps." (PMID 38297356, 2024).
benign tumors (1 paper, 2020). "A 6-biomarker model (HE4, CA125, CXCL1, ITGAV, CEACAM1, IL-10RB and age) was found to be the best model for discrimination between benign tumors and EOC including borderline tumors." (PMID 33075095, 2020).
brain diseases (1 paper, 2022). "Following our previous paper on the role of CXCL1 in physiology and in bone, muscle and brain diseases, in this paper, we present the importance of CXCL1 in other organs and tissues in the physiological state and in noncancer diseases of the oral cavity and abdominal organs." (PMID 35806156, 2022).
gastrointestinal disorders (1 paper, 2023). "Thus, specific or combined inflammatory mediators such as C-X-C motif chemokine ligand 1 (also known as GroA and upregulated in developed ileus), are believed to be viable biomarkers for the early detection of gastrointestinal disorders." (PMID 37670946, 2023).
neurodegenerative disease (1 paper, 2013). A disorder of the central nervous system characterized by gradual and progressive loss of neural tissue and neurologic function. "Increased production ofastrocytic CCL2 and CXCL1 was observed in nerve tissue damaged by brain ischemiaand neurodegenerative diseases." (PMID 23627909, 2013).
CXCL1 also shares sentences with these, for which no sentence is quoted: portal hypertension (7 papers); renal failure (5); lupus nephritis (4); peripheral neuropathy (4); metabolic disorders (3); multiple myeloma (3); pancreatic adenocarcinoma (3); staphylococcus aureus infection (3); status epilepticus (3); allergic asthma (2); astrocytoma (2); bronchitis (2); cardiac disease (2); Chlamydia infection (2); chronic prostatitis (2); cyst (2); demyelination (2); dermatitis (2); encephalomyelitis (2); Encephalopathy (2); endocervical adenocarcinoma (2); gastrointestinal disease (2); gestational hypertension (2); Gingival bleeding (2); immune deficiency (2); inflammatory skin disease (2); irritable bowel syndrome (2); Parkinson disease (2); psychotic disorder (2); ulcers (2).
A further 129 diseases each share a sentence with CXCL1 in 1 paper.